MMP9 (matrix metallopeptidase 9)
Diseases named in the same sentence as MMP9 in open-access papers (continued):
Sharing a sentence is not in itself a finding about the gene and the disease.
ZIKV infection (4 papers, 2020 to 2023). "Collectively, these results suggested that MMP9, induced by ZIKV infection, caused SCB hyperpermeability." (PMID 32302362, 2020). "Here, we explored the mechanisms underlying matrix metalloproteinase 9 (MMP9)-modulated ZIKV infection in mice." (PMID 32302362, 2020). "In addition, collagen IV was barely detected in infected WT mice, but was abundant in infected MMP9-/- mice, suggesting that ZIKV infection resulted in MMP9-mediated loss of collagen IV." (PMID 32302362, 2020). "Collectively, we concluded that ZIKV infection promoted the expression of MMP9 which was further stabilized by NS1 induced K63-linked polyubiquitination to affect the TJPs/ type IV collagen network, thereby disrupting the BTB and facilitating ZIKV entry into the testes." (PMID 32302362, 2020). "Our previous study revealed that matrix metalloproteinase 9 (MMP9) was up-regulated by ZIKV infection in cultured primary mSCs and A129 mice." (PMID 33534087, 2021). "ZIKV infection affected the permeability of the blood-testis barrier (BTB) through MMP9 mediated degradation of TJPs and type IV collagens that are critically involved in the maintenance of the BTB." (PMID 32302362, 2020). "In this study, we revealed that matrix metalloproteinase 9 (MMP9) was upregulated by ZIKV infection in cell culture and in A129 mice." (PMID 32302362, 2020). "We also examined the expression of MMP9 in human embryonic kidney cells (HEK293T) after ZIKV infection at different multiplicity of infection (MOI)." (PMID 32302362, 2020). "To identify the physiological relevance of elevated MMP9 in the pathogenesis of orchitis caused by ZIKV infection, we used Ifnar-blocked C57BL/6 wild type (WT) and C57BL/6 MMP9-knockout (MMP9-/-) mice as animal models." (PMID 32302362, 2020). "First, we observed significant upregulation of MMP9 both in vivo and in vitro after ZIKV infection, consistent with the results of quantitative proteomic analysis using ZIKV-infected A129 mouse testes." (PMID 32302362, 2020). "Here, we initially measured whether ZIKV infection could induce the expression and activity of MMP9 in vitro." (PMID 32302362, 2020). "Accordingly, in this study, we evaluated the roles of MMP9 in ZIKV infection in vivo and in vitro." (PMID 32302362, 2020). "We showed that MMP9 was upregulated by ZIKV infection both in vivo and in vitro." (PMID 32302362, 2020). "In our study, we found that MMP9 mRNA and protein expression was upregulated by ZIKV infection." (PMID 32302362, 2020). "The expression and activity of MMP9 in primary mSCs, primary mouse embryonic fibroblasts (MEFs), and adenocarcinomic human alveolar basal epithelial cells (A549) were measured after ZIKV infection." (PMID 32302362, 2020). "ZIKV infection in WT mice produced a short duration of viremia in the blood, with the highest level observed 1 day after infection and clearance observed at day 3; similar results were observed for MMP9-/- mice." (PMID 32302362, 2020). "Furthermore, we found that MMP9 protein levels were upregulated in sera following ZIKV infection." (PMID 32302362, 2020). "Taken together, these findings demonstrated that MMP9 was upregulated both in time-dependent and ZIKV-dose dependent manners by ZIKV infection." (PMID 32302362, 2020). "In in vivo and in vitro studies, MMP-9 expression and activity were increased during ZIKV infection and the ZIKV non-structural protein 1 interacted with MMP-9 and promoted its K63-linked polyubiquitination to prevent proteosome degradation." (PMID 36142454, 2022). "On the other hand, mRNA levels for MMP-9, ADAMTS-4, and ADAMTS-5, which have been reported associated with PNN degradation, and gelatinase/collagenase activity were not significantly elevated in the brain during ZIKV infection." (PMID 37496706, 2023).
Achalasia (3 papers, 2015 to 2020). A disorder of esophageal motility characterized by the inability of the lower esophageal sphincter to relax during swallowing and by inadequate or lacking peristalsis in the lower half of the body of the esophagus. "Finally, we tested the paradigm of remnant epitopes generating autoimmunity (REGA) for achalasia-associated autoantigens by evaluating whether autoantigenic proteins are cleaved by MMP-9 into remnant epitopes." (PMID 30449890, 2018). "Distinctly higher ratios of MMP-9/MMP-2 and activated MMP-9/proMMP-9 are found in the sera of achalasia patients than the controls, and MMP-9 can be used as an innate immune effector for binding to novel substrates in achalasia." (PMID 31947787, 2020). "On the basis of higher zymolysis levels of activated MMP-9 in achalasia sera and biopsies, in situ expression was evaluated on a number of biopsy samples." (PMID 30449890, 2018). "Finally, we document that MMP-9 cleaves a number of known and novel achalasia-associated autoantigens into remnant epitopes and therefore might be a major player during the pathogenesis of achalasia." (PMID 30449890, 2018). "The percentages of MMP-9‒expressing cells were significantly higher in patients with achalasia when compared with those producing MMP-2." (PMID 30449890, 2018). "Although activated forms are less stable and less commonly detected than the proforms, we detected significantly more activated MMP-9 monomers in achalasia than in control sera." (PMID 30449890, 2018). "On zymography analysis, EJOO patients had lower MMP-9 levels compared to both achalasia patients and healthy controls and lower MMP-2 levels compared to controls." (PMID 30449890, 2018). "To study the possible role of MMP-9 in generating autoantigenic remnant epitopes, we first listed all known autoantigenic proteins in achalasia." (PMID 30449890, 2018). "Overall, basal MMP-2 levels were lower in achalasia in comparison with control levels and the ratio of MMP-9 versus MMP-2 was increased in achalasia." (PMID 30449890, 2018). "We thus defined several new substrates of MMP-9 and added these to the list of achalasia autoantigens." (PMID 30449890, 2018). "Type III achalasia patients showed increased expression of MMP-9, followed by type II, type I and transplant donors." (PMID 30449890, 2018). "The presence of MMP-2 and MMP-9 proteoforms was analyzed in sera of two cohorts of achalasia patients." (PMID 30449890, 2018). "For this, a comprehensive list was made of all known achalasia autoantigens and these molecules were evaluated as known or novel substrates of MMP-9." (PMID 30449890, 2018). "The myenteric plexus of esophageal tissue from achalasia patients showed a statistically significant increase in MMP-9 percentage versus tissue control group." (PMID 26078981, 2015). "In particular, MMP-9 immunoreactivity increased significantly according to type of achalasia." (PMID 30449890, 2018). "Additionally, we documented achalasia-associated autoantigens PNMA2, Ri, GAD65, and VIP as novel MMP-9 substrates." (PMID 30449890, 2018). "A second finding was a significant increase in activated MMP-9 in achalasia sera." (PMID 30449890, 2018). "The data suggest that the ratio MMP-9/MMP-2 might be useful as novel serum marker for achalasia." (PMID 30449890, 2018). "Previously, MMP-9 and its inhibitor (tissue inhibitor of metalloproteinase-1 or TIMP-1) have been detected by immunohistochemistry in biopsies of achalasia patients." (PMID 30449890, 2018). "The increased serum levels of gelatinases prompted us to investigate achalasia tissues as a possible source of MMP-2 and MMP-9." (PMID 30449890, 2018). "In many inflammatory diseases, the ratio of MMP-9 versus MMP-2 is a useful marker, as was corroborated here in achalasia versus controls." (PMID 30449890, 2018).
Achalasia (continued). "Ratios of MMP-9/MMP-2 and act/proform MMP-9 of EJOO patients were similar as observed in healthy controls, in contrast to the significant increase observed in achalasia patients versus healthy controls." (PMID 30449890, 2018). "We showed significantly increased ratios of MMP-9/MMP-2 and activated MMP-9/proMMP-9 in sera of achalasia patients (n = 88) versus controls (n = 60)." (PMID 30449890, 2018). "MMP-9-positive and MMP-2-positive cells were more abundant in achalasia (n = 49) versus control biopsies from transplant donors (n = 10)." (PMID 30449890, 2018). "Nonetheless, the number of MMP-9+ cells in types II and III achalasia was higher when compared to type I achalasia." (PMID 26078981, 2015). "Whereas it is difficult to speculate about the origin of the circulating MMP-9, the presence of many MMP-9-expressing cells in achalasia biopsies suggest at least a trigger from the local tissue." (PMID 30449890, 2018).
acute leukemia (3 papers, 2016 to 2025). A clonal (malignant) hematopoietic disorder with an acute onset, affecting the bone marrow and the peripheral blood. "Our results show that BMSCs could promote the expression of MMP-9 in HL60 cells, which may explain the fact that the BMM can contribute to the proliferation of acute leukemia cells." (PMID 33146708, 2020).
AIDS (3 papers, 2016 to 2024). A syndrome resulting from the acquired deficiency of cellular immunity caused by the human immunodeficiency virus (HIV). "To the best of our knowledge, we have shown for the first time that HIV-activated MMP-9 may facilitate the spread of HSV, which is an opportunistic infection for HIV/AIDS." (PMID 29775175, 2018).
allergic rhinitis (3 papers, 2019 to 2024). Inflammation of the nasal mucous membranes caused by an IgE-mediated response to external allergens. "The targets of 48 putative therapeutic components in the treatment of allergic rhinitis include IL6, TNF, CXCL8, ICAM1, ILA, MMP9, IL10, and IL1B." (PMID 31611923, 2019).
Alport syndrome (3 papers, 2016 to 2021). A rare renal disease characterized by glomerular nephropathy with hematuria progressing to end-stage renal disease (ESRD), frequently associated with sensorineural deafness, and occasionally with ocular anomalies. "Elevated expression of MMP-9 is observed in fibrotic renal cortex from X-linked Alport syndrome dogs." (PMID 26942026, 2016). "Consistent with reduced fibrosis, the expression levels of fibrotic genes Mmp9/12, α-Sma, and Tgf-β were lower in kidney tissues of metformin- or losartan-treated Col4a5 G5X Alport syndrome mice." (PMID 33782421, 2021). "Expression of MMPs occurs with disease progression in Alport syndrome and MMP-2, MMP-9, and MMP-12 have been linked to GBM alterations." (PMID 29167507, 2017). "Although not specifically investigated in Alport syndrome, in vitro keratinocyte cell migration towards fibronectin was documented to be stimulated by plasminogen and plasmin by a MMP-9 dependent mechanism and cooperatively interacting with β1 integrins." (PMID 26942026, 2016).
anaphylaxis (3 papers, 2014 to 2023). An acute hypersensitivity reaction that occurs from exposure to an allergen. "Genetic variations at the IL-18 locus (IL18R1 and IL18RAP) were associated with exercise-induced anaphylaxis, while MMP9 and OSM provide evidence for the involvement of innate immune pathways." (PMID 36569939, 2022). "Thirdly, MMP-9 activation and overproduction are proved to be associated with the occurrence and development of some inflammatory reaction and anaphylaxis." (PMID 24708644, 2014). "Hub genes identified here (IL1R2, FOS, MMP9, DUSP1, and CLEC4D) represent a whole blood gene signature of anaphylaxis with STEMI predisposition and provide candidate diagnostic and therapeutic targets for follow-up studies." (PMID 37469874, 2023). "IL1R2, FOS, MMP9, DUSP1, and CLEC4D were screened and identified as hub genes shared by anaphylaxis and STEMI." (PMID 37469874, 2023). "Taking the intersection of six algorithms (DMNC, Stress, MCC, Degree, Closeness, Radiality) in cytoHubba, we found 6 hub genes shared by anaphylaxis and STEMI: IL1R2, S100A12, FOS, MMP9, DUSP1, and CLEC4D." (PMID 37469874, 2023). "In this study, we identified four approved drugs that have the potential to be repurposed against hub genes involved in anaphylaxis complicated STEMI, including anakinra, baclofen, andecaliximab, and albuterol targeting IL1R2, FOS, MMP9, and DUSP1, respectively." (PMID 37469874, 2023). "Due to the critical role of MMP9 in STEMI and anaphylaxis, andecaliximab might be a promising strategy to curtail anaphylaxis complicated STEMI." (PMID 37469874, 2023).
ANCA-associated vasculitis (3 papers, 2015 to 2020). "It was demonstrated by others that rituximab may decrease serum MMP-9 levels in antineutrophil cytoplasmic antibody (ANCA)-associated vasculitis (AAV) treated with rituximab." (PMID 25190551, 2015).
angle-closure glaucoma (3 papers, 2011 to 2024). The sudden increase of intraocular pressure, resulting in pain and an abrupt decrease in visual acuity. "Several studies investigated the association of MMP polymorphisms, particularly MMP9, with the risk of open-angle or angle-closure glaucoma in different populations." (PMID 39769228, 2024). "This is the first study to suggest an association between MMP9 polymorphisms and PACG in the Australian Caucasian population, and one of the first studies to investigate angle closure glaucoma genetics in the Caucasian population." (PMID 21655354, 2011).
anxiety disorder (3 papers, 2021 to 2025). A category of psychiatric disorders which are characterized by anxious feelings or fear often accompanied by physical symptoms associated with anxiety. "In fact, MMP9 has been associated with an increased susceptibility to anxiety disorders as well as showing elevated levels in other psychiatric illnesses." (PMID 34034683, 2021). "Similarly, the single nucleotide polymorphisms (SNPs) in the human homologs of MMP9 were significantly associated with susceptibility to anxiety disorders." (PMID 35624976, 2022).
asbestosis (3 papers, 2017). A lung disorder caused by inhalation of asbestos fibers. "Secondly, YKL-40 correlated with adipsin and MMP-9, markers that were also found to be increased in subjects with asbestosis in the present study." (PMID 28588347, 2017). "Adipsin and MMP-9 levels were increased in subjects with asbestosis." (PMID 28588347, 2017). "MMP2 and MMP9 were correlated with each other in all groups, except for the asbestosis group." (PMID 28348451, 2017). "Our work also found that the protein levels of both MMP2 and MMP9 were not correlated with levels of HMGB1 in sera of patients with asbestosis or MM." (PMID 28348451, 2017). "Interestingly, both MMP2 and MMP9 serum levels were not correlated with HMGB1 in ARDs, including PP, asbestosis and MPM." (PMID 28348451, 2017).
Atrophy (3 papers, 2021 to 2025). Any weakening or degeneration, especially through lack of use. "Likewise, it is essential to highlight the correlation between elevated mediator levels and increased marginal bone atrophy in cigarette smokers (MMP-9 and IL-1β) and e-cigarette users (IL-1β)." (PMID 37526741, 2023).
B-cell acute lymphoblastic leukemia (3 papers, 2020 to 2021). A neoplasm of lymphoblasts committed to the B-cell lineage, typically composed of small to medium-sized blast cells. "Interestingly, leukemic-cell-derived TNF induced matrix metalloproteinase 9 (MMP-9) expression by the bone marrow microenvironment through TNFR1, thus contributing to acute lymphoblastic B-cell leukemia progression." (PMID 33917839, 2021).
Barrett esophagus (3 papers, 2010 to 2020). Esophageal lesion lined with columnar metaplastic epithelium which is flat or villiform. "We suggested that quantification of MMP-9 in Barrett’s esophagus might be useful to identify patients at higher risk for progression to esophageal adenocarcinoma." (PMID 23202950, 2012). "Amazingly, there may be another link in the network; leptin has been shown to increase the gene expression of HB-EGF and extracellular release of HB-EGF in human oesophageal adenocarcinoma cells and this was blocked by MMP9 inhibitor." (PMID 32906753, 2020).
benign ovarian tumors (3 papers, 2012 to 2021). "The serum levels of S100A11 and MMP-9 in patients with EOC were higher than those in patients with benign ovarian tumor and in healthy women, and the expression levels of S100A11 and MMP-9 were positively correlated." (PMID 33763485, 2021). "By cluster analysis, only MT1-MMP, MMP-7 and MMP-9 could distinguish malignant serous tumors from borderline and benign ovarian tumors." (PMID 22200690, 2012). "Serum levels of S100A11 and MMP9 were detected in patients with EOC, patients with benign ovarian tumor, and healthy women." (PMID 33763485, 2021).
benign prostatic hyperplasia (3 papers, 1994 to 2024). A non-cancerous nodular enlargement of the prostate gland. "Elevated MMP9 expression was reported in PCa patients compared to those with benign prostatic hyperplasia." (PMID 39336161, 2024).
bone inflammatory diseases (3 papers, 2014 to 2025). "Cigarette smoking was associated with the up-regulation of MMP-1 and MMP-9 in the nasal tissues of patients with airway inflammatory diseases, and with AE osteitis, and with therapeutic resistence." (PMID 31653934, 2019). "Future investigations should assess the therapeutic potential of MMP-9 inhibitors in this preclinical model and explore their applicability in inflammatory bone disorders." (PMID 40244002, 2025). "MMP-9 also plays a critical role in the pathophysiology of osteitis in CRS and MMP-9 overexpression, which is steroid-independent, suggesting its relevance to therapeutic resistance." (PMID 31653934, 2019). "MMP-9 plays an important role in the pathophysiology of osteitis in CRS22." (PMID 31653934, 2019). "The interplay between MMP-9 expression and sICAM-1 release may exert an important role in the regulation of bone inflammatory diseases." (PMID 24502696, 2014). "Matrix metalloproteinase-9 (MMP-9) has been shown to be induced by cytokines including TNF-α and may contribute to bone inflammatory diseases." (PMID 24502696, 2014).
breast disease (3 papers, 2009 to 2022). "Somiari and coworkers have suggested that circulating MMP-2 and MMP-9 levels are associated with disease severity and may permit the classification of patients with breast disease." (PMID 19889214, 2009). "Our results also document a positive correlation between MMP-9 serum levels and the severity score of breast disease (p < 0.006)." (PMID 19889214, 2009). "In our study, we attempted to evaluate the expression of MMP-9/NGAL complex in serum of patients with breast disease and correlate it with disease severity." (PMID 19889214, 2009). "However, future studies including a higher number of patients could elucidate the significance of serum MMP-9/NGAL expression in patients with breast disease." (PMID 19889214, 2009). "The aim of our study is to evaluate the serum levels of MMP-9, NGAL and MMP-9/NGAL complex in patients with breast abnormalities and investigate their correlation with breast disease severity." (PMID 19889214, 2009). "Our data suggest that MMP-9 and NGAL are positively correlated with breast disease severity, with a potential clinical utility as early markers of breast disease status." (PMID 19889214, 2009). "Significant correlations were observed between MMP-9 and NGAL serum levels and breast disease severity score (r = 0.229, p < 0.006 and r = 0.206, p < 0.01, respectively), whereas a non-significant correlation was found for their complex." (PMID 19889214, 2009).
bronchiolitis (3 papers, 2019 to 2026). Inflammation of the bronchioles characterized by swelling of the bronchioles and mucus accumulation. "We found a protective effect of higher MMP‐9 on bronchiolitis risk (aOR 0.45, 95% CI, 0.27–0.73, padj = 0.001)." (PMID 40952045, 2026). "To investigate the association of IFN‐γ, p62, and MMP‐9 with the incidence of bronchiolitis hospitalization, we performed logistic regressions adjusting for confounders." (PMID 40952045, 2026).